TBC1D3L (TBC1 domain family member 3L)
Description:
Acts as a GTPase activating protein for RAB5. Does not act on RAB4 or RAB11 (By similarity).
Tractability: Antibody: UniProt places it where antibodies can reach, with medium confidence; its Gene Ontology location is reachable by antibodies, with medium confidence. PROTAC: UniProt records ubiquitination sites on it.
Gene: Protein-coding gene on chromosome 17 (37,978,154 to 37,989,389, reverse strand). Ensembl gene ENSG00000274512.
Subcellular location: Cell membrane
Subcellular location (Human Protein Atlas): Vesicles
Gene Ontology:
Molecular function: GTPase activator activity
Cellular component: plasma membrane; endosome; membrane
Genetic constraint (gnomAD): Loss-of-function variants: 0 observed, 2.24 expected, observed/expected ratio (o/e) 0, 90% interval 0 to 1.25. That is too few expected variants to judge how well the gene tolerates losing a copy. Missense variants: 2 observed, 35.24 expected, observed/expected ratio (o/e) 0.0568, 90% interval 0.022 to 0.18. Synonymous variants: 0 observed, 11.72 expected, observed/expected ratio (o/e) 0, 90% interval 0 to 0.25.
Homologues: Orthologues: chimpanzee TBC1D3B (96% identical). Paralogues in human: TBC1D3D (99% identical), TBC1D3 (99% identical), TBC1D3C (99% identical), TBC1D3I (99% identical), TBC1D3H (99% identical), TBC1D3E (99% identical), TBC1D3F (99% identical), TBC1D3G (99% identical), TBC1D3K (99% identical), TBC1D3B (99% identical), TBC1D26 (30% identical), USP6NL (29% identical), and 33 more.